RNF213 (ring finger protein 213)
Diseases named in the same sentence as RNF213 in open-access papers (continued):
Sharing a sentence is not in itself a finding about the gene and the disease.
lung carcinoma (3 papers, 2021 to 2026). "The second most mutated gene was RNF213, which was recently identified as an early-stage lung cancer biomarker." (PMID 38137511, 2023). "In GGO patients, RNF213 was mutated more frequently in early‐stage lung cancer compared to benign diseases (P < 0.05)." (PMID 33200540, 2021). "Significant findings of the study: In peripheral venous blood and tumor tissue, RNF213 gene mutated more frequently in lung cancer than benign pulmonary nodules." (PMID 33200540, 2021). "In all 70 samples of our study, RNF213 gene mutated more frequently in lung cancer than benign diseases (P = 0.006, two ‐tailed)." (PMID 33200540, 2021). "The RNF213 gene was mutated in 25% of lung cancer samples in the validation set of 28 samples and showed high specificity (100%)." (PMID 33200540, 2021). "We first found an RNF213 gene mutation in ctDNA of early‐stage lung cancer, and this mutation was found at a significantly different rate than in benign lung disease." (PMID 33200540, 2021). "RNF213 gene mutated in 12 lung cancer (25.5%) and 0 benign disease samples." (PMID 33200540, 2021). "Mutation of the RNF213 gene in peripheral blood may be a high specificity biomarker for the assisted early diagnosis of lung cancer in pulmonary nodules." (PMID 33200540, 2021). "In addition, the underlying mechanisms of the RNF213 gene in the development of lung cancer requires further study." (PMID 33200540, 2021). "RNF213 gene mutated more frequently in lung cancer than benign diseases (P = 0.006, two‐tailed)." (PMID 33200540, 2021). "What this study adds: Detection mutation of the RNF213 gene in peripheral blood may be a high specificity method for the assisted early diagnosis of lung cancer in pulmonary nodules." (PMID 33200540, 2021). "High expression of the RNF213 gene in lung cancers and low expression in benign diseases were seen by immunohistochemistry." (PMID 33200540, 2021). "In the training set, RNF213, KMT2D, CSMD3 and LRP1B were mutated more frequently in early‐stage lung cancer than in benign disease." (PMID 33200540, 2021). "LRP1B, KMT2D, RNF213 and CSMD3 gene mutations were significantly more common in lung cancer than in benign disease (P < 0.05)." (PMID 33200540, 2021). "In the training set, the RNF213, KMT2D, CSMD3 and LRP1B genes were mutated more frequently in early‐stage lung cancer (27 cases) than in benign nodules (15 cases) (P < 0.05)." (PMID 33200540, 2021). "We found a novel RNF213 gene with high specificity in peripheral blood ctDNA in assisted diagnosis of lung cancer." (PMID 33200540, 2021). "In other words, all patients with RNF213 gene wild‐type in peripheral blood had benign disease in our study and about 25% patients with RNF213 gene mutant type were lung cancer." (PMID 33200540, 2021). "The RNF213 gene was mutated in 25% of lung cancer patients and was not mutated in benign diseases, but KMT2D, CSMD3 and LRP1B were mutated less in both groups." (PMID 33200540, 2021). "The results showed that the RNF213 gene was mutated in 27.8% of lung cancer samples and in none of the benign disease samples (P < 0.05), with a similarly high specificity." (PMID 33200540, 2021). "We detected RNF213 gene mutations in 10 (10/36, 27.8%) lung cancer samples and no samples in the benign disease group (P < 0.05)." (PMID 33200540, 2021). "RNF213 gene mutations were observed more frequently in early‐stage lung cancer, but not in benign nodules." (PMID 33200540, 2021). "The RNF213 gene had a high specificity in distinguishing lung cancer from benign disease." (PMID 33200540, 2021). "A total of 25.9% of lung cancer patients showed RNF213 gene mutations, and no lung cancer was observed in benign disease patients." (PMID 33200540, 2021). "High expression of RNF213, KMT2D and CSMD3 was observed in lung cancer tissues, and low expression of these genes was observed in benign disease tissues." (PMID 33200540, 2021).
lung carcinoma (continued). "The number of the test genes RNF213, KMT2D, CSMD3 and LRP1B detected in lung cancer samples was five, five, three and two, respectively." (PMID 33200540, 2021). "In the training set, the RNF213, LRP1B, KMT2D and CSMD3 genes had statistically significant differences in the sequenced data in lung cancer compared to benign disease." (PMID 33200540, 2021). "The number of missense mutations in the LRP1B, KMT2D, RNF213 and CSMD3 genes was eight (8/27, 29.6%), seven (7/27, 25.9%), seven (7/27, 25.9%) and six (6/27, 22.2%) in the lung cancer group, respectively, and none of the genes were mutated in the benign disease control group." (PMID 33200540, 2021).
Obesity (3 papers, 2016 to 2024). Accumulation of substantial excess body fat. "RNF213 located in the nuclear region may be associated with immune response, obesity, defense response, stress response, DNA repair, cancer, and ubiquitin-binding." (PMID 37273690, 2023).
Renal artery stenosis (3 papers, 2022 to 2025). The presence of stenosis of the renal artery. "Therefore, MMD, PAH, and renal artery stenosis may be the specific manifestations of pathophysiological changes caused by RNF213 mutation, which can be summarized as spectrums of RNF213 vasculopathy." (PMID 35401401, 2022). "In addition, several reports documented that RNF213 gene mutations not only increase the risk of MMD but also are associated with intracranial atherosclerosis and systemic vascular diseases, such as PPAS, renal artery stenosis, and coronary artery disease." (PMID 35401401, 2022).
stenosis (3 papers, 2025). "Stenosis progression rates were notably higher in the RNF213 variant group (25.7%; 9/35 cases) than in the RNF213 wild-type group (8.7%; 9/104 cases)." (PMID 39531151, 2025). "Stenosis in the anterior circulation was present in 100% (13/13) of the patients with the RNF213 p.Arg4810Lys variant and 74% (146/196) of those with the wild-type." (PMID 39958261, 2025). "Stenosis progression occurred in 25.7% (9/35) of the RNF213 variant group and 8.7% (9/104 cases) of the RNF213 wild-type group." (PMID 39531151, 2025). "This implied a difference in the vascular stenosis mechanism attributed to the RNF213 p.Arg4810Lys variant." (PMID 39531151, 2025). "In addition to intracranial artery stenosis, RNF213 p.Arg4810Lys is associated with extracranial artery stenosis and maximum intima-media thickness." (PMID 39958261, 2025). "In fact, patients carrying the RNF213 p.4810K variant treated with nilotinib might be more susceptible in developing IC arterial stenosis or occlusion, mostly reported in Asian patients." (PMID 41473461, 2025).
Aicardi-Goutières syndrome (2 papers, 2016 to 2020). "Our findings suggest placing RNF213-triggered MMD among the vasculopathies that are caused by impaired nucleotide processing, such as Aicardi-Goutières syndrome or SLE." (PMID 32342250, 2020). "Given that Type I IFN overproduction (Aicardi–Goutieres syndrome) is complicated by MMD and RNF213 is highly activated by IFNs, pro-inflammatory signals enhance IFN overproduction, which then activates RNF213 transcription." (PMID 26662949, 2016).
Aortic dissection (2 papers, 2022 to 2025). Aortic dissection refers to a tear in the intimal layer of the aorta causing a separation between the intima and the medial layers of the aorta. "Specifically, in a panel sequencing study of 702 patients with sporadic aortic dissection, pathogenic or likely pathogenic RNF213 variants were identified in 3.7% (26/702) of patients." (PMID 40869987, 2025). "Recent large-scale Chinese cohort studies and reviews have demonstrated a clear association between the RNF213 gene and sporadic aortic dissection." (PMID 40869987, 2025). "Transcriptome analysis revealed that the messenger RNA expression of RNF213 was linked with that of FBN1, the most frequent pathogenetic gene in aortic dissection, suggesting that reduced RNF213 expression might be associated with the interruption of aortic development." (PMID 35455046, 2022). "Furthermore, transcriptome analysis has shown a correlation between RNF213 mRNA expression and that of FBN1 (the gene most frequently implicated in aortic dissection)." (PMID 40869987, 2025).
arterial diseases (2 papers, 2017 to 2025). "Etiological evaluation should also consider underlying connective tissue disorders or arteriopathies, including Ehlers-Danlos, Marfan, and RNF213-related syndromes." (PMID 41281093, 2025).
bacillary dysentery (2 papers, 2025). "In support of this hypothesis, we demonstrate here that a causative agent of bacillary dysentery, Shigella flexneri, uses the type III secretion system (T3SS) effector IpaH1.4 to induce the degradation of RNF213." (PMID 39282383, 2025).
CADASIL (2 papers, 2024 to 2025). "Notably, the RNF213 p.Arg4810Lys variant carriers were identified in 6 out of 124 (4.8%) Japanese patients with CADASIL, indicating a significantly higher prevalence than the 1.5% found in the general population." (PMID 40869930, 2025). "The combined presence of both NOTCH3 and RNF213 variants may lead to a diagnosis of CADASIL due to an accelerated clinical course or a mixed phenotype." (PMID 40869930, 2025). "Recently, an individual case report described a patient with CADASIL who also exhibited RNF213-related vasculopathy." (PMID 40869930, 2025).
cerebral aneurysms (2 papers, 2021). "We also assumed that the frequency of RNF213 in the general Japanese population and cerebral aneurysms would be approximately 1.5%9,33." (PMID 34773068, 2021). "Furthermore, the frequency of RNF213 (c.14576G>A) in Japanese patients with cerebral aneurysms (CAN) was lower than that in patients with ICS and comparable (ranging from 0 to 2.1%) to that in control subjects with no vascular lesions." (PMID 34680863, 2021). "Studies on RNF213 and cerebral aneurysms (AN), which did not focus on the site of origin or morphology, could not elucidate the relationship between the two." (PMID 34680863, 2021).
cervical cancer (2 papers, 2020 to 2023). A primary or metastatic malignant neoplasm involving the cervix. "Therefore, the role of RNF213 in cervical cancer is required for further investigation and must be validated as a prognostic factor to measure clinical outcomes during cervical cancer treatment." (PMID 32718341, 2020).
Cognitive impairment (2 papers, 2020 to 2022). Abnormal cognition is characterized by deficits in thinking, reasoning, or remembering. "Indeed, only 27% (682/2566) of all patients with IS underwent RNF213 p.R4810K genotyping because of difficulties in providing informed consent caused by issues with old age, impaired consciousness, cognitive impairment, and advanced frailty." (PMID 41582976, 2022).
depression (2 papers, 2018 to 2020). "Finally, another connection between RNF213 and depression is formed by the let-7 family of miRNAs, i.e., short RNA sequences that were found to suppress the common variant of the RNF213 gene." (PMID 32727556, 2020).
dyslipidemia (2 papers, 2021). "When patient mutations induce dysfunction of RNF213 or sGC, vascular damage caused by homocysteine, dyslipidemia or infection may be amplified, leading to chronic inflammation." (PMID 34381413, 2021). "However, very recently it has been suggested a potential link between MA pathogenesis and lipid metabolism, although neither study showed direct association between RNF213 mutations and dyslipidemia." (PMID 34948203, 2021).
familial hypercholesterolemia (2 papers, 2024 to 2025). An inheritable form of hyperlipidemia, in which there are excess lipids in the blood. "Another Japanese study confirmed RNF213 Arg4810Lys’s involvement with familial hypercholesterolemia genes, which may cause more severe stenosis or occlusion in the anterior circulation and increase the risk of intracranial major artery stenosis/occlusion (ICASO)." (PMID 40869185, 2025). "RNF213 Arg4810Lys coexisted with PCSK9 Glu32Lys (familial hypercholesterolemia) in a Japanese patient with multiple intracranial major artery stenoses and asymptomatic intracranial atherosclerotic stenosis (ICAS)." (PMID 40869185, 2025).
liver disease (2 papers, 2021). "RNF213 variants in GWAS analyses suggestively associated (p-value ~ E−03) with diabetic polyneuropathy, portal hypertension, diabetic retinopathy and abnormal glucose." (PMID 33472578, 2021).
myocardial infarction (2 papers, 2016 to 2025). Gross necrosis of the myocardium, as a result of interruption of the blood supply to the area, as in coronary thrombosis. "Building upon the association with cerebrovascular pathology, the RNF213 p.R4810K variant has also been robustly linked to early-onset coronary artery disease (CAD) and myocardial infarction (MI)." (PMID 40869987, 2025).
neuroblastoma (2 papers, 2020 to 2024). Neuroblastoma (NB) is the most common solid, extracranial childhood tumor. "Thus, different stress conditions were applied to murine bone-marrow-derived macrophages (BMDM), murine embryonal fibroblasts (MEF), the human neuroblastoma cell line (SH-SY5Y), and human umbilical vein endothelial cells (HUVEC), documenting the subsequent regulation of Rnf213 mRNA." (PMID 32342250, 2020). "However, neither murine Rnf213 was changed in MEF after 24 h, nor human RNF213 in neuroblastoma SH-SY5Y cells after 24 h and 36 h." (PMID 32342250, 2020).
neurofibromatosis (2 papers, 2023). A hereditary neoplastic syndrome in which tumors grow in the nervous system. "To evaluate the role of genetic factors other than NF1 in the onset of Moyamoya in Neurofibromatosis patients, we re-sequenced the entire coding region, including the intron–exon boundaries of RNF213, the major susceptibility gene for MMD in the three groups of patients." (PMID 36980803, 2023). "Our comprehensive analysis in an unselected exclusively pediatric sample shows that RNF213 patients and neurofibromatosis patients represented the two largest subgroups." (PMID 37012328, 2023). "A search for RNF213 deleterious variants may provide clinical benefits when extended to MMS cases as well, as demonstrated by the two children with neurofibromatosis, RNF213 variants and PCA involvement in our cohort." (PMID 37012328, 2023).
Achalasia (1 paper, 2017). A disorder of esophageal motility characterized by the inability of the lower esophageal sphincter to relax during swallowing and by inadequate or lacking peristalsis in the lower half of the body of the esophagus. "Several susceptibility genes have been identified for MMD: MMD-2 (gene: RNF213), MMD-5 (ACTA2), and MMD-6 with achalasia (GUCY1A3)." (PMID 28617845, 2017).
Alzheimer disease (1 paper, 2019). A progressive, neurodegenerative disease characterized by loss of function and death of nerve cells in several areas of the brain leading to loss of cognitive function such as memory and language. "We were also able to identify proteins exclusively observed in Alzheimer’s disease (i.e., RNF213) or only detected in samples not affected by the disease (i.e., CNTN1) after the enrichment process." (PMID 31253170, 2019).
anaplastic large cell lymphoma (1 paper, 2015). Anaplastic large cell lymphoma (ALCL) is a rare and aggressive peripheral T-cell non-Hodgkin lymphoma, belonging to the group of CD30-positive lymphoproliferative disorders, which affects lymph nodes and extranodal sites. "Ring finger protein 213 (RNF213) has been reported as a fusion partner of ALK and MYC in anaplastic large cell lymphoma and inflammatory myofibroblastic tumor." (PMID 26089344, 2015).
aneurysmal diseases (1 paper, 2021). "Also, some articles report that variants of ubiquitination associated genes might predispose to aneurysmal diseases, for example RNF213 variants for CA/ASH." (PMID 34895131, 2021).
aortic coarctation (1 paper, 2023). "Among RNF213 patients with MMD, patient 73577, a girl carrying the maternally inherited p.(Thr1705Lys) and p.(Leu1054Met) variants in cis, presented with mid-aortic syndrome, a rare form of aortic coarctation which has been recently linked to RNF213 as well as NF1 variants." (PMID 37012328, 2023).
bacterial sepsis (1 paper, 2024). "While Eif2ak2 and Herc6 are implicated in bacterial sepsis, Rnf213 is associated with ubiquitylation of LPS, and Casp1 is a key factor in the inflammatory response in bacterial infection as detected in common upregulation." (PMID 38792580, 2024).
bone metastasis (1 paper, 2024). Transfer of a neoplasm from its primary site to bones. "The RNF213 wild type was significantly correlated with bone metastasis (p = 0.047)." (PMID 39338204, 2024).
cerebral artery stenosis (1 paper, 2025). A cerebrovascular disorder characterized by an abnormal narrowing of a cerebral artery. "A recent study reviewed 52 patients with cerebral artery stenosis without MMD and found that patients carrying the RNF213 p.R4810K mutation had a higher risk of stenosis progression." (PMID 39191959, 2025).
Chorea (1 paper, 2021). Chorea (Greek for 'dance') refers to widespread arrhythmic involuntary movements of a forcible, jerky and restless fashion. "This case may renew interest in the concept of RNF213-related vasculopathy and the pathophysiological mechanisms behind chorea in ICA stenosis." (PMID 33482763, 2021). "Alternatively, as RNF213 regulates vascular endothelial function and angiogenesis, dysregulation may impair the neurovascular unit and damage basal ganglia circuitry, contributing to the development of chorea." (PMID 33482763, 2021).
chronic myeloid leukemia (1 paper, 2023). "In chronic myeloid leukemia (CML), there is a fusion between the SLC26A11 gene and RNF213 gene." (PMID 37664112, 2023).
COVID-19 (1 paper, 2022). A disease caused by infection with severe acute respiratory syndrome coronavirus 2. "Ring Finger Protein 213 (RNF213), an E3 ubiquitin ligase and component of the proteasomal degradation machinery that is suppressed in monocytes from severe COVID-19 patients." (PMID 36143338, 2022).
dissection (1 paper, 2025). The separation and isolation of tissues for surgical purposes, or for the analysis or study of their structures. "Among other determined types of disease, RNF213 p.Arg4810Lys was found in patients with cerebral artery dissection (6.7%; 1/15) but not in those with perforating branch infarction, including SVO and BAD (0/84) and subarachnoid haemorrhage (0/5)." (PMID 39958261, 2025).
Duchenne muscular dystrophy (1 paper, 2025). Duchenne muscular dystrophy (DMD) is a neuromuscular disease characterized by rapidly progressive muscle weakness and wasting due to degeneration of skeletal, smooth and cardiac muscle. "RNF213 Arg4810Lys may also act as a risk modifier in Duchenne muscular dystrophy (DMD)." (PMID 40869185, 2025).
familial disease (1 paper, 2020). "Although the RNF213 4810G > A variant has never been detected in Caucasians, there are rare missense RNF213 variants, which have been associated with MMD in Caucasians, especially those with childhood-onset or familial disease." (PMID 32182997, 2020).
gram-negative bacterial infections (1 paper, 2023). Infections caused by bacteria that show up as pink (negative) when treated by the gram-staining method. "In the anti-bacterial activity of RNF213, researchers have unveiled an initial set of mechanisms to combat Gram-positive and Gram-negative bacterial infections." (PMID 37655297, 2023).
Graves disease (1 paper, 2025). Graves' disease is an autoimmune disorder that leads to overactivity of the thyroid gland (hyperthyroidism).It is caused by an abnormal immune system response that causes the thyroid gland to produce too much thyroid hormones. "Another compound heterozygous case of the RNF213 Arg4810Lys mutation was observed along with the Ser3986Asn mutation in a patient with Graves’ disease 182,183]." (PMID 40869185, 2025). "RNF213 Arg4810Lys was also reported alongside Ser3986Asn in a diagnosed Japanese female with MMD concurrent with Graves’ disease (GD)." (PMID 40869185, 2025).